RAMP2 (receptor activity modifying protein 2)
Description:
Accessory protein that interacts with and modulates the function of G protein-coupled receptors including calcitonin gene-related peptide type 1 receptor (CALCRL) and calcitonin receptor (CALCR). Required for the transport of CALCRL to the plasma membrane. Together with CALCRL, form a receptor complex for adrenomedullin/ADM. Together with CALCR, act as a receptor complex for calcitonin/CT/CALC. Together with CALCR, also act as a receptor complex for amylin/IAPP.
Tractability: Small molecule: a structure with a bound ligand is known; it has a binding pocket of medium quality. Antibody: UniProt places it where antibodies can reach, with high confidence; its Gene Ontology location is reachable by antibodies, with high confidence; UniProt predicts a signal peptide or a membrane-spanning region.
Gene: Protein-coding gene on chromosome 17 (42,758,447 to 42,763,041, forward strand). Ensembl gene ENSG00000131477.
Subcellular location: Cell membrane
Subcellular location (Human Protein Atlas): Vesicles
Pathways (Reactome):
Signal Transduction: Calcitonin-like ligand receptors; G alpha (s) signalling events
Cellular responses to stimuli: High laminar flow shear stress activates signaling by PIEZO1 and PECAM1:CDH5:KDR in endothelial cells
Gene Ontology:
Molecular function: adrenomedullin binding; adrenomedullin receptor activity; coreceptor activity; protein binding
Biological process: adenylate cyclase-activating G protein-coupled receptor signaling pathway; adherens junction assembly; adrenomedullin receptor signaling pathway; amylin receptor 2 signaling pathway; angiogenesis; bicellular tight junction assembly; calcium ion transport; negative regulation of endothelial cell apoptotic process; negative regulation of vascular permeability; positive regulation of gene expression; protein localization to plasma membrane; protein transport; receptor internalization; vasculogenesis; basement membrane assembly; cellular response to hormone stimulus; cellular response to vascular endothelial growth factor stimulus; G protein-coupled receptor signaling pathway; heart development; positive regulation of angiogenesis; regulation of blood pressure; sprouting angiogenesis; vascular associated smooth muscle cell development; intracellular protein transport; regulation of G protein-coupled receptor signaling pathway
Cellular component: adrenomedullin receptor complex; cell surface; cytoplasm; plasma membrane; receptor complex; clathrin-coated pit; lysosome; membrane
Genetic constraint (gnomAD): Loss-of-function variants: 10 observed, 16.3 expected, observed/expected ratio (o/e) 0.61, 90% interval 0.38 to 1.04. The upper end of that interval is the gene's LOEUF score, 1.04, which puts it in group 4 of 6, group 1 being the genes least tolerant of losing a copy. Missense variants: 169 observed, 196.2 expected, observed/expected ratio (o/e) 0.86, 90% interval 0.76 to 0.98. Synonymous variants: 78 observed, 73.81 expected, observed/expected ratio (o/e) 1.06, 90% interval 0.88 to 1.28.
Homologues: Orthologues: chimpanzee RAMP2 (99% identical), macaque RAMP2 (95% identical), dog RAMP2 (80% identical), pig RAMP2 (76% identical), mouse Ramp2 (67% identical), rat Ramp2 (67% identical), guinea pig RAMP2 (62% identical), rabbit RAMP2 (51% identical), tropical clawed frog RAMP2 (37% identical), zebrafish ramp2 (22% identical). Paralogues in human: RAMP1 (25% identical), RAMP3 (23% identical).
Diseases named in the same sentence as RAMP2 in open-access papers:
RAMP2 is named in the same sentence as 55 diseases in open-access papers, as found by Europe PMC text mining. Sharing a sentence is not in itself a finding about the gene and the disease. The quoted sentences say what the papers report.
melanoma (5 papers, 2017 to 2023). A malignant, usually aggressive tumor composed of atypical, neoplastic melanocytes. "AM, CLR, and RAMP2/3 expressions have been reported in melanoma and it has been demonstrated that tumor-associated macrophages, through AM, favor melanoma growth and angiogenesis." (PMID 36980580, 2023). "(Left) Transplantation of melanoma cells into drug-inducible vascular endothelial cell-specific RAMP2 knockout (DI-E-RAMP2-/-) mice suppresses local growth, whereas metastasis to distant organs is enhanced." (PMID 35625516, 2022). "Antibodies were used to label serial sections of melanoma tissue with corresponding AM, CLR, RAMP2, and RAMP3 proteins." (PMID 36497391, 2022). "Melanoma cells were also strongly labelled for AM, CLR, RAMP2, and RAMP3 in melanoma metastatic tissue (patients #1, 2, 3), while mild staining can be observed in melanoma primitive tissue (patient #4)." (PMID 36497391, 2022). "In the clinic, most human melanoma tissues were positive for CRLR, RAMP2, and RAMP3 –apart from AM–, while their expression levels were much lower in control healthy samples." (PMID 33489885, 2020). "Furthermore, in melanomas, the expression levels of AM, CLR, RAMP2, and RAMP3 have been shown to be higher than those in the control tissues." (PMID 29179449, 2017).
migraine (3 papers, 2022 to 2024). "Future research should investigate whether RAMP2 predominance over RAMP1 in the meningeal vasculature results in altered migraine susceptibility or in a different response to anti-migraine medication in these patients." (PMID 39390360, 2024). "OPRM1 emerges as a pivotal hub, instigating the activation of GNAS and GNB1, subsequently influencing proteins such as RAMP1, RAMP2, RAMP3, CALCB, CALCR, and SLC5A2 all implicated in migraine attacks." (PMID 39215033, 2024). "Migraine patients infused with ADM developed migraine attacks, suggesting that the ADM-mediated CLR/RAMP2 signaling represents a potential target for migraine treatment." (PMID 36569288, 2022). "Interestingly, the observations in the current study showing two types of expression patterns of RAMP1 and RAMP2 in HMMA donors, could suggest that also two types of (migraine) patients exist, who possibly respond differently to treatment." (PMID 39390360, 2024).
pancreatic cancer (3 papers, 2016 to 2023). "The expression of AM, CLR, and RAMP2/3 has been reported in pancreatic cancer, and a high level of AM is associated with a decrease in disease-free survival." (PMID 36980580, 2023). "In the present study, pancreatic cancer cells secreted high levels of adrenomedullin (ADM), and CD11b+ myelomonocytic cells expressed all components of ADM receptors, including GPR182, CRLR, RAMP2 and RAMP3." (PMID 27391260, 2016).
dilated cardiomyopathy (2 papers, 2017 to 2022). Cardiomyopathy which is characterized by dilation and contractile dysfunction of the left and right ventricles. "Induction of RAMP2 deficiency in adult mice resulted in the spontaneous onset of a dilated cardiomyopathy-like finding which was lethal." (PMID 35625516, 2022).
gastric cancer (2 papers, 2017 to 2023). A primary or metastatic malignant neoplasm involving the stomach. "C11_VWF were characterized by co‐expressing marker genes of fibroblasts (COL1A1, FAP, VIM, ACTA2) and endothelial cells (VWF, PECAM1, CLDN5, FLT1, RAMP2), which resembled a subgroup of cells undergoing an EMT transition in gastric cancer." (PMID 38115703, 2023). "Our results show that the expression levels of AM, CRLR, RAMP1, RAMP2, and RAMP3 are higher in gastric cancer tissues than in the adjacent non-tumor gastric tissues, and the patients with the lower expression levels of AM lived longer (p=0.0258)." (PMID 29179449, 2017).
glioblastoma (2 papers, 2014 to 2021). The most malignant astrocytic tumor (WHO grade IV). "Relevant studies have proved that the mRNAs of CALCRL/RAMP2 and CALCRL/RAMP3 are highly expressed in glioblastoma cell lines." (PMID 34712139, 2021). "Real-time quantitative RT-PCR was used to study expression of AM, RAMP2, RAMP3, and CLR in pilocytic astrocytoma and glioblastoma." (PMID 25475159, 2014). "Interestingly, although there were not differences in RAMP2 or RAMP3 expression, AM mRNA expression was induced in glioblastoma whereas it was barely detectable in pilocytic astrocytoma when subjected to hypoxic conditions." (PMID 25475159, 2014).
heart failure (2 papers, 2015 to 2022). Inability of the heart to pump blood at an adequate rate to meet tissue metabolic requirements. "For example, RAMP2 expression in the heart has been shown to be significantly up-regulated in mouse models of heart failure." (PMID 26198634, 2015). "Cardiac myocyte-specific RAMP2 knockout mice showed early onset of heart failure as well as abnormal mitochondrial morphology and function, whereas RAMP3-/- mice exhibited abnormal cardiac lymphatics and a delayed onset of heart failure." (PMID 35625516, 2022).
hepatoma (2 papers, 2009 to 2021). "Given the physiological relevance of hepatocytes for GCG signalling and the cell line dependence of RAMP activity, we next examined this phenomenon in Huh7 hepatoma cells, which express low levels of endogenous RAMP2." (PMID 34271220, 2021). "The interaction of RAMP2 with GCGR has functional consequences: here, we demonstrate that up-regulation of RAMP2 acutely increases agonist-stimulated cAMP production in hepatoma cells, a phenomenon that has previously been shown in other non-hepatocyte cell lines." (PMID 34271220, 2021). "Down-regulated genes include RAMP2 and PPARGC1A, and their inactivation or under-expression was shown to contribute to lung cancer and hepatoma development respectively." (PMID 20015407, 2009). "Subcellular localisation of GCGR in the presence and absence of RAMP2 was investigated using confocal microscopy, trafficking and radioligand binding assays in human embryonic kidney (HEK293T) and human hepatoma (Huh7) cells." (PMID 34271220, 2021).
Hyperglycemia (2 papers, 2014 to 2022). An increased concentration of glucose in the blood. "Our results showed that glucose dose-dependently increased mRNA expressions of ADM and its receptor components CRLR, RAMP2 and RAMP3 suggesting the association between hyperglycemia and elevated ADM in diabetic patients." (PMID 35390031, 2022). "From the results summarized above, we initially hypothesized that STZ-induced hyperglycemia would induce more severe glomerular lesions in RAMP2+/− than in WT kidneys." (PMID 24505304, 2014). "To determine whether the tubular damage was caused by hyperglycemia, we administered insulin (glargine at a dose of 0.5–2 U daily) and STZ for 2 weeks, which normalized their blood glucose levels but did not mitigate the damage seen in RAMP2+/− kidneys." (PMID 24505304, 2014). "We therefore considered the renal tubular injury seen in RAMP2+/− kidneys to be a direct effect of STZ, not a secondary effect of hyperglycemia." (PMID 24505304, 2014).
Hypertension (2 papers, 2015 to 2017). The presence of chronic increased pressure in the systemic arterial system. "We also found that Ramp2-/- placentas–similar to Adm-/- and Calcrl-/- placentas–exhibit persistent smooth muscle cell coverage of maternal spiral arteries–a hallmark sign of preeclampsia, a dangerous hypertensive disease of pregnancy." (PMID 28727763, 2017). "Consistently, one human study found that Ramp2 mRNA expression in the umbilical artery and uterus of women was negatively correlated with pregnancy-induced hypertension." (PMID 28727763, 2017). "Of note, RAMP-1 expression was about 3.5-times higher compared to RAMP-2 expression in the normotensive state in both mouse lines and, more importantly, increased to a 6.6-times higher RAMP-1 expression over that of RAMP-2 due to a significant hypertension-induced drop in RAMP-2 expression." (PMID 25860809, 2015). "Whereas hypertension did not alter RAMP-1 expression (droplet digital (dd) PCR) in either mouse line, RAMP-2 expression dropped significantly in both mouse lines by about 65%." (PMID 25860809, 2015).
acute respiratory distress syndrome (1 paper, 2025). Progressive and life-threatening pulmonary distress in the absence of an underlying pulmonary condition, usually following major trauma or surgery. "In an LPS-induced acute respiratory distress syndrome (ARDS) mouse model, RAMP2 and RAMP3 were found to play crucial roles inflammatory modulation functions of ADM." (PMID 40565016, 2025).
breast carcinoma (1 paper, 2025). "Subsequently, the role of these driver genes in DCIS progression was validated through ADM2 knockdown and RAMP2 overexpression, which, as expected, inhibited the proliferation and migration of breast cancer cell lines." (PMID 41150812, 2025). "CCK-8 assays demonstrated that ADM2 knockdown significantly suppressed the proliferation of BT-549 and MDA-MB-231 cells, while overexpression of RAMP2 also inhibited proliferation across multiple breast cancer cell lines." (PMID 41150812, 2025). "Gene set enrichment analysis (GSEA) revealed the biological functions of RAMP2 and ADM2, while in vitro functional assays demonstrated that ADM2 knockdown and RAMP2 overexpression in breast cancer cell lines significantly suppressed cellular proliferation and invasion." (PMID 41150812, 2025). "Therefore, we further evaluated the effects of ADM2 and RAMP2 on the biological functions of breast cancer cell lines in vitro." (PMID 41150812, 2025). "In order to further explore the effect of ADM2 and RAMP2 on breast cancer cells, siRNAs of ADM2 and the overexpression vector for RAMP2 were constructed and transfected into BT-549 and MDA-MB-231 breast cancer cell lines, respectively." (PMID 41150812, 2025). "After constructing siRNAs targeting ADM2 and RAMP2 overexpression plasmids, our results revealed that downregulating ADM2 expression significantly inhibited the proliferation and infiltration of breast cancer cells." (PMID 41150812, 2025).
chromophobe renal cell carcinoma (1 paper, 2023). Chromophobe renal cell carcinoma is a rare subtype of renal cell carcinoma, originating from the intercalating cells of the collecting ducts and macroscopically manifesting as a well-circumscribed, highly lobulated, solid tumor that is usually diagnosed at an early stage. "AM, CLR, and RAMP2 were observed in the carcinomatous epithelial compartment of chromophobe renal cell carcinoma (CRCC), and RAMP3 was only found in the inflammatory cells that infiltrated tumors." (PMID 36980580, 2023).
Cirrhosis (1 paper, 2021). A chronic disorder of the liver in which liver tissue becomes scarred and is partially replaced by regenerative nodules and fibrotic tissue resulting in loss of liver function. "The level of up-regulation achieved in our system (3-fold) may also not have been sufficient to bring out a phenotype; however, it is worth noting that this level is comparable to the increase in hepatic RAMP2 observed in a rodent model of cirrhosis." (PMID 34271220, 2021).
colorectal cancer (1 paper, 2023). A primary or metastatic malignant neoplasm that affects the colon or rectum. "CLR, RAMP2, and RAMP3 expressions have been reported in colorectal cancer; high levels of AM, CLR, RAMP2, and RAMP3 correlate with lymph nodes and distant metastasis, and a high level of AM correlates with a low disease-free survival." (PMID 36980580, 2023).
COVID-19 (1 paper, 2025). A disease caused by infection with severe acute respiratory syndrome coronavirus 2. "Based on howRAMP2 affects adrenomedullin, this study demonstrates that the RAMP2 upregulation observed in the lung tissue of COVID-19 infected patients is most likely a compensatory response to lung injury caused by COVID-19, and is aimed at mitigating damage and inflammation." (PMID 41141600, 2025).
diabetic nephropathy (1 paper, 2014). "To evaluate their susceptibility to renal injury, we examined RAMP2+/− mice and their WT littermates in a STZ-induced diabetic nephropathy model." (PMID 24505304, 2014).
Glomerular sclerosis (1 paper, 2014). Accumulation of scar tissue within the glomerulus. "We found, however, that RAMP2+/− mice administered STZ did not exhibit accelerated glomerular sclerosis when compared to WT mice." (PMID 24505304, 2014).
liver cirrhosis (1 paper, 2017). "Endothelial cell-specific RAMP2 knockout mice even show liver cirrhosis-like changes with aging." (PMID 29022011, 2017).
liver fibrosis (1 paper, 2017). "We previously reported that RAMP2 is the key modulator of the endogenous vasoprotective peptide adrenomedullin, and that vascular endothelial cell-specific RAMP2 knockout mice show vascular inflammation and liver fibrosis." (PMID 29022011, 2017).
lung disease (1 paper, 2014). "Ramp2 [Receptor (calcitonin) activity modifying protein 2], Acaa2 (Acetyl-Coenzyme A acyltransferase 2), Mdh1 (Malate dehydrogenase 1, NAD), and Tspan8 (Tetraspanin 8) are enriched mRNAs in the lungs and are involved in lung disease." (PMID 25070658, 2014).
migraine headache (1 paper, 2019). "CLR/RAMP1, or CGRP receptor, antagonists have been developed for thetreatment of migraine headache and osteoarthritis pain; whereas CLR/RAMP2, orADM receptor, antagonists are being developed for the treatment of tumorgrowth/metastasis." (PMID 31150417, 2019).
orchitis (1 paper, 2013). Inflammation of one or both testes due to viral or bacterial infections. "In a rat model, bacterial lippolysaccharide (LPS) induced atypical orchitis, and LPS treatment upregulated the expression of IMD and one of its receptor component proteins, i.e. receptor activity modifying protein 2 (RAMP2)." (PMID 23750251, 2013).
primary open-angle glaucoma (1 paper, 2025). "Reportedly, genetic mutations in RAMP2 in mice disrupt the AM-RAMP2/CLR and cAMP signaling pathways, leading to primary open-angle glaucoma through retinal ganglion cell death." (PMID 40465267, 2025).
prostate carcinoma (1 paper, 2023). A carcinoma that arises from epithelial cells of the prostate gland. "CLR and RAMP2/3 have been reported in prostate cancer, and a high level of AM has been associated with a high Gleason score." (PMID 36980580, 2023). "Moreover, the use of a polyclonal antibody designed to block all the receptor components of AM (RAMP2, RAMP3, and CLR) decreased both proliferation and invasion of prostate cancer cells, tumor weight, metastasis, and lymphatic vasculature." (PMID 36980580, 2023).
pulmonary fibrosis (1 paper, 2020). Chronic progressive interstitial lung disorder characterized by the replacement of the lung tissue by connective tissue, leading to progressive dyspnea, respiratory failure, or right heart failure. "RAMP2 overexpression in myofibroblasts was reported to enhance survival and reduce pulmonary fibrosis in the bleomycin mouse model by sensitizing adrenomedullin signaling." (PMID 32244228, 2020).
Sepsis (1 paper, 2025). Sepsis is defined as life-threatening organ dysfunction caused by a dysregulated host response to infection. "Notably, CALCRL downregulation in sepsis disrupts its interaction with RAMP2/3 (receptor activity-modifying proteins), thereby impairing adrenomedullin clearance and compromising its protective anti-inflammatory functions." (PMID 40761792, 2025).
Splenomegaly (1 paper, 2025). Abnormal increased size of the spleen. "Additionally, the increase in spleen weight due to EAU was greater in the RAMP2 (±) mice than in the RAMP2 (+/+) mice, similar to the findings in AM (±) mice, suggesting that the AM-RAMP2 system plays a role in the inflammatory response and the splenomegaly caused by EAU." (PMID 40465267, 2025).
uveitis (1 paper, 2025). An inflammatory process affecting a part of or the entire uvea. "AM exerts an anti-inflammatory effect in uveitis by activating Tregs and M2 macrophages through RAMP2." (PMID 40465267, 2025). "Exogenous AM administration tended to increase RAMP2 expression, whereas RAMP3 expression remained suppressed, suggesting that AM administration ameliorates the pathogenesis of uveitis via RAMP2 but not RAMP3." (PMID 40465267, 2025).